RNU6-1010P (RNA, U6 small nuclear 1010, pseudogene)
Gene: Small nuclear RNA gene on chromosome 7 (131,054,886 to 131,054,992, reverse strand). Ensembl gene ENSG00000199627.
Homologues: Orthologues: chimpanzee U6 (100% identical), macaque U6 (92% identical), dog U6 (85% identical), dog U6 (84% identical), mouse Gm23407 (64% identical). Paralogues in human: RNU6-1152P (87% identical), RNU6-15P (87% identical), RNU6-166P (87% identical), RNU6-20P (87% identical), RNU6-211P (87% identical), RNU6-41P (87% identical), RNU6-820P (87% identical), RNU6-1145P (86% identical), RNU6-16P (86% identical), RNU6-19P (86% identical), RNU6-25P (86% identical), RNU6-29P (86% identical), and 1286 more.